CROT (carnitine O-octanoyltransferase)
Description:
Beta-oxidation of fatty acids. The highest activity concerns the C6 to C10 chain length substrate. Converts the end product of pristanic acid beta oxidation, 4,8-dimethylnonanoyl-CoA, to its corresponding carnitine ester.
Synonyms: COT
Tractability: PROTAC: ubiquitination databases record sites on it; its protein half-life has been measured.
Target class: Group translocator; Transporter
Gene: Protein-coding gene on chromosome 7 (87,345,664 to 87,399,800, forward strand). Ensembl gene ENSG00000005469.
Subcellular location: Peroxisome
Subcellular location (Human Protein Atlas): Vesicles
Pathways (Reactome):
Metabolism: Beta-oxidation of pristanoyl-CoA
Protein localization: Peroxisomal protein import
Gene Ontology:
Molecular function: carnitine O-octanoyltransferase activity; acyltransferase activity
Biological process: fatty acid beta-oxidation; fatty acid metabolic process; generation of precursor metabolites and energy; medium-chain fatty acid metabolic process; carnitine metabolic process; coenzyme A metabolic process; fatty acid beta-oxidation using acyl-CoA oxidase
Cellular component: peroxisome; cytosol; peroxisomal matrix
Genetic constraint (gnomAD): Loss-of-function variants: 48 observed, 60.9 expected, observed/expected ratio (o/e) 0.79, 90% interval 0.62 to 1. The upper end of that interval is the gene's LOEUF score, 1, which puts it in group 4 of 6, group 1 being the genes least tolerant of losing a copy. Missense variants: 504 observed, 543.41 expected, observed/expected ratio (o/e) 0.93, 90% interval 0.86 to 1. Synonymous variants: 148 observed, 182.89 expected, observed/expected ratio (o/e) 0.81, 90% interval 0.71 to 0.93.
Homologues: Orthologues: chimpanzee CROT (99% identical), macaque CROT (97% identical), mouse Crot (86% identical), pig CROT (86% identical), dog CROT (85% identical), rat Crot (85% identical), rabbit CROT (83% identical), guinea pig CROT (79% identical), tropical clawed frog crot (67% identical), zebrafish crot (62% identical), Caenorhabditis elegans T20B3.1 (32% identical), Drosophila melanogaster CROT (32% identical), and 1 more. Paralogues in human: CRAT (33% identical), CHAT (30% identical), CPT1A (30% identical), CPT2 (29% identical), CPT1B (28% identical), CPT1C (27% identical).
Diseases named in the same sentence as CROT in open-access papers:
CROT is named in the same sentence as 22 diseases in open-access papers, as found by Europe PMC text mining. Sharing a sentence is not in itself a finding about the gene and the disease. The quoted sentences say what the papers report.
ovarian carcinoma (3 papers, 2019 to 2023). A malignant neoplasm originating from the surface ovarian epithelium. "Another study has shown that CROT expression was downregulated in ovarian cancer and that CROT has tumor-suppressive activities in ovarian cancer cell lines." (PMID 37307919, 2023). "Among nine of the 11 multidrug-resistant ovarian cancer cell line variants, the drug-resistant gene MDR1 (ABCB1) is co-expressed with multiple genes located in 7q21, including CROT and CDK6." (PMID 31295943, 2019).
breast carcinoma (2 papers, 2019 to 2023). "Copy number gains were acquired in the genes all located on chromosome 7 including CROT, which potentially drives the development of docetaxel resistance in breast cancer cells." (PMID 31295943, 2019).
cholelithiasis (2 papers, 2025). The presence of crystallized deposits forming in the gallbladder or biliary tree, primarily composed of cholesterol, bilirubin, and bile. "Specifically, genetically predicted higher levels of CROT (OR = 1.08, 95% CI = 1.04–1.12) were positively associated with an increased risk of cholelithiasis, while higher levels of SPHK2 (OR = 0.75, 95% CI = 0.65–0.86) were associated with a decreased risk of cholelithiasis." (PMID 40958306, 2025).
colorectal cancer (2 papers, 2022 to 2023). A primary or metastatic malignant neoplasm that affects the colon or rectum. "LncRNA EGOT modulates apoptosis and proliferation by the miR-33b-5p/CROT signaling in colorectal cancer." (PMID 38006396, 2023). "Furthermore, the positive regulation of TGF-β on fatty acid oxidation has been observed in breast and colorectal cancer cells, implying that TGF-β may also be involved in CROT-mediated OC cell behaviors." (PMID 36120434, 2022).
melanoma (2 papers, 2023 to 2025). A malignant, usually aggressive tumor composed of atypical, neoplastic melanocytes. "One recent study has revealed that CROT is upregulated in a mouse model of melanoma circulating tumor cells." (PMID 37307919, 2023). "Consistent with our results, this study revealed that CROT knockdown resulted in decreased survival of cells grown in suspension and reduced metastatic propensity of melanoma cells." (PMID 37307919, 2023). "Knockdown of FAO-related genes, such as CROT or CRAT, in a melanoma cell line led to a significant delay in metastasis in the xenograft model." (PMID 41155168, 2025).
atherosclerosis (1 paper, 2024). A disease characterized by the build-up of fatty material and calcium deposition in the arterial wall resulting in partial or complete occlusion of the arterial lumen. "How lipid dysfunction specifically promotes calcification potential remains unknown, thus the discovery that CROT inhibition reduces calcification potential in a mouse model for atherosclerosis provided the rationale to assess more carefully CROT function in normolipidemic mice in the present study." (PMID 39076376, 2024).
dyslipidemia (1 paper, 2024).
leukemia (1 paper, 2019). A malignant (clonal) hematologic disorder, involving hematopoietic stem cells and characterized by the presence of primitive or atypical myeloid or lymphoid cells in the bone marrow and the blood.
prostate tumor (1 paper, 2019). "Similar to FECH, CROT does not consistently differentially express between the primary prostate tumor and normal prostate." (PMID 31295943, 2019).
tumor (4 papers, 2019 to 2024). "CROT is involved in fatty acid metabolism, and alterations in its expression are linked to changes in cancer cell metabolism and potential effects on tumor growth and patient prognosis." (PMID 38962012, 2024). "Future studies will be required to determine the contexts in which CROT acts as a tumor suppressor or therapeutic target." (PMID 37307919, 2023). "But in the TCGA dataset, CROT is significantly differentially expressed in tumor samples (p = 0.005)." (PMID 31295943, 2019). "In conclusion, CROT expression is downregulated in OC tissues and PTX-resistant OC cells and functions as a tumor suppressor which affects OC cell behaviors and the prognosis of OC patients." (PMID 36120434, 2022). "The expression level of FECH and CROT is not significantly changed between normal and primary tumor based on the MSKCC dataset." (PMID 31295943, 2019).
cancer (3 papers, 2023 to 2025). A tumor composed of atypical neoplastic, often pleomorphic cells that invade other tissues. "In this context, targeting enzymes like CROT, CRAT, CPT2, CPT1, and CAC, which regulate lipid transport and utilization, may inhibit cancer cell growth by disrupting their metabolic flexibility." (PMID 40001519, 2025).
infection (2 papers, 2011 to 2017). The state of being infected such as from the introduction of a foreign agent such as serum, vaccine, antigenic substance or organism. "These include perilipin 2 (PLIN2), which was increased subsequent to primary infection by E. acervulina and E. maxima, as well as prostaglandin reductase 1 (PTGR1), CD36, and carnitine O-octanoyltransferase (CROT), which were decreased following E. acervulina primary infection." (PMID 22140460, 2011).
kidney disease (1 paper, 2023). "From the datamining sources through network biology conducted by Cytoscape, it was found that ACADM, CROT, CRAT, and ACADS are the most prominent genes involved in the function of LC and in the pathology of kidney disease." (PMID 36836532, 2023).
CROT also shares sentences with these, for which no sentence is quoted: depression (2 papers); Anxiety (1); Cardiovascular Disease (1); Fanconi anemia (1); glioblastoma (1); hepatocellular carcinoma (1); laryngeal carcinoma (1); liver fibrosis (1); mitochondrial disease (1).